CDK4 (cyclin dependent kinase 4)
Diseases named in the same sentence as CDK4 in open-access papers (continued):
Sharing a sentence is not in itself a finding about the gene and the disease.
breast cancer (continued). "Our findings strongly suggest that the JNK pathway acts as a tumour suppressor in ER+ breast cancer, and that JNK pathway status may be a biomarker of response to combination endocrine and CDK4/6 inhibitor therapy." (PMID 40826108, 2025). "The aberrant activation of the cyclin-dependent kinase 4 and 6 (CDK4/6) pathway, independent of mitogenic signaling, engenders uncontrolled breast cancer cell proliferation." (PMID 40058234, 2025). "In this multicenter retrospective study, it was observed that, in HR + HER2− advanced breast cancer patients progressing under CDK 4/6 inhibitor therapy, a short duration of CDK4/6 inhibitor treatment increased physicians’ preference for chemotherapy as a subsequent treatment." (PMID 41156245, 2025). "Looking ahead, combining dual-targeted therapies involving CDK4/6 and the BCL-2 pathway may provide an effective strategy for treating HR+ breast cancer." (PMID 40104496, 2025). "The combination of CDK4/6i and ET has reshaped treatment for HR+/HER2− breast cancer." (PMID 39605351, 2025). "Simultaneous blockade of the estrogen receptor, CDK4/6, and PAM pathways may optimize antitumor control in the treatment-naïve advanced breast cancer setting." (PMID 40711480, 2025). "Although disappointing, these results are unsurprising because CDK4/6is are not used as monotherapy in other cancers, including breast cancer where it is most often used in combination with hormone therapy." (PMID 40282469, 2025). "For the first time, we elucidate the molecular characteristics of early adaptation and resistance to CDK4/6i + ET, using clinically relevant drug concentrations, in HR+, HER2− breast cancer and identify therapeutic strategies to overcome acquired resistance in this setting." (PMID 40141282, 2025). "In light of these promising preliminary efficacy and safety results, a phase III study evaluating gedatolisib combined with a CDK4/6 inhibitor and fulvestrant as first-line treatment for patients with ET-resistant HR+, HER2− advanced breast cancer was initiated (NCT06757634; VIKTORIA-2)." (PMID 40711480, 2025). "The combination of cyclin-dependent kinase 4/6 (CDK4/6) inhibitors with endocrine therapy (ET) has become the first-line treatment for advanced or recurrent Hormone Receptor (HR)-positive, HER2-negative (HR+/HER2-) breast cancer since around 2017." (PMID 40075731, 2025). "The combination of CDK4/6 inhibitors (CDK4/6i) with endocrine therapy (ET) has been approved by the FDA as a first-line treatment regimen for patients with advanced hormone receptor-positive, HER2-negative (HR+/HER2-) breast cancer." (PMID 40142360, 2025). "In addition, palbociclib, a selective inhibitor of CDK4/6, already demonstrated good efficacy in two large phase III trials on advanced ER+ breast cancer (NCT01740427 and NCT01942135)." (PMID 40003864, 2025). "CDK4 and CDK6 inhibitors that target cell cycle mechanisms have already been introduced into the clinic and used to treat breast cancer, and may have a profound impact on targeted therapies for other tumor types (Álvarez-Fernández and Malumbres, 2020)." (PMID 40303979, 2025). "According to the European Society for Medical Oncology (ESMO) guidelines, CDK4/6 inhibitors in combination with endocrine therapy are recommended as the standard of care for the treatment of hormone receptor-positive, HER2-negative advanced breast cancer." (PMID 40405072, 2025). "The use of CDK4/6 inhibitors in combination with endocrine therapy (ET) is now considered the standard of care for patients with advanced or metastatic ER-positive, HER2-negative breast cancer." (PMID 40244189, 2025). "CDK4/6 inhibitors effectively suppress tumor growth through multiple pathways, and several agents in this class have been approved by the FDA for treating patients with HR + /HER2- advanced breast cancer." (PMID 41259313, 2025).
breast cancer (continued). "Preclinical and clinical trials investigating the combination of CDK4/6 inhibitors with ICIs for breast cancer suggest that combined use does not significantly enhance responses compared to CDK4/6 inhibitor monotherapy." (PMID 40058234, 2025). "The combination regimen of a cyclin-dependent kinase 4/6 (CDK4/6) inhibitor and endocrine therapy (e.g., an aromatase inhibitor) is the current first-line standard-of-care treatment for patients with metastatic ER+/HER2– breast cancer." (PMID 40598566, 2025). "Palbociclib was the first CDK4/6 inhibitor to be FDA approved in 2015 for the treatment of postmenopausal women with locally advanced or metastatic hormone receptor-positive, HER2-negative breast cancer." (PMID 40075623, 2025). "CDK4/6 inhibitors could benefit a broader population and enhance long-term efficacy for HR+, HER2-breast cancer patients, including those with N0 or Stage II disease." (PMID 40717978, 2025). "Based on a large number of clinical trial data, patients with ER-high and HER2-negative advanced breast cancer have clearly benefited from CDK4/6 inhibitor combined with endocrine therapy, but there are still some patients with poor prognosis." (PMID 39020297, 2024). "Therefore, this study investigated the efficacy and safety of CDK4/6 inhibitors in the adjuvant and neoadjuvant treatment of HR-positive/HER2-negative early breast cancer." (PMID 39329126, 2024). "Interestingly, CDK4/6 can be activated beyond the MAPK pathway via the estrogen receptor (ER) signaling pathway, which is common in breast cancer." (PMID 38732242, 2024). "These patients had, however, all received a systemic therapy for breast cancer, most commonly endocrine therapy with or without a CDK4/6 inhibitor." (PMID 39199595, 2024). "Selective CDK4/6 inhibitors (CDK4/6i), such as palbociclib, abemaciclib and ribociclib have received FDA approval for the treatment of estrogen receptor-positive (ER + )/HER2-negative breast cancer." (PMID 39695080, 2024). "The recent FDA approval of three CDK4/6 inhibitors (CDK4/6is), palbociclib, ribociclib, and abemaciclib, has led to the rapid adoption of targeted treatment of CDK4/6 as first-line or second-line therapy in advanced ER + /HER2- breast cancer." (PMID 38831405, 2024). "We further found that RET silencing using RET-specific siRNAs significantly inhibited the growth of MCF7-derived ER+ breast cancer cells resistant to combined CDK4/6i and endocrine therapy (MPF-R) but not of T47D-derived double-resistant cell line (TPF-R)." (PMID 39931212, 2024). "This is the first study to examine the potential of an RR inhibitor DDX in combination with CDK4/6 inhibitor palbociclib for the treatment of ER+ and ER− breast cancers with or without palbociclib resistance." (PMID 38473336, 2024). "Currently, selective ER modulators (SERM), selective ER degraders (SERD), aromatase inhibitors (AIS), ovarian function inhibitors (OFS), mTOR inhibitors, and cell Cyclin-dependent kinase 4/6 (CDK4/CDK6) inhibitors are the main endocrine and targeted therapies for HR+ breast cancer patients." (PMID 38459605, 2024). "The addition of CDK4/6 inhibitors to endocrine therapy has significantly improved both PFS and OS in this patient population, establishing this combination as the standard of care for advanced HR+ HER2-negative breast cancer." (PMID 39797256, 2024). "The introduction of CDK4/6i, initially in the metastatic setting and more recently in the adjuvant setting, have made significant progress in the treatment of patients with HER2-negative, HR-positive breast cancer." (PMID 38800404, 2024). "The combination of CDK4/6 inhibitors (CDK4/6i) and endocrine therapy (ET) is currently the standard first-line treatment for patients with metastatic hormone receptor positive (HR+), and HER2-negative (HER2-) breast cancer." (PMID 39267829, 2024).
breast cancer (continued). "In addition to palbociclib, other phase III trials have evaluated the efficacy of CDK4/6 inhibitors in combination with fulvestrant in patients with HR-positive, HER 2-negative advanced breast cancer whose disease had progressed on endocrine therapy." (PMID 37955764, 2024). "For advanced HR-positive breast cancer in premenopausal women, OFS is essential to induce a postmenopausal state, especially when using targeted medications like cyclin-dependent kinase 4/6 (CDK4/6) inhibitors alongside endocrine therapy." (PMID 38709374, 2024). "Palbociclib, a well-tolerated and effective CDK4/6 inhibitor was initially granted accelerated approval in February 2015, in combination with letrozole for the treatment of estrogen receptor (ER)-positive, HER2-negative advanced breast cancer." (PMID 37955764, 2024). "Though three CDK4/6 inhibitors are currently approved in the treatment of breast cancer, none have been approved for HNC despite early clinical and preclinical studies demonstrating their potential application." (PMID 38612819, 2024). "Others demonstrated that abemaciclib (CDK4/CDK6 inhibitor) significantly enhanced anti-tumor responses in cell lines, animal models and breast cancer patients by increasing the capacity of tumor cells to present antigen and reducing Treg levels resulting in decreased Treg/CD8 T-cell ratio." (PMID 39007281, 2024). "In breast cancer, we examined the combination of Palbociclib (CDK4/6 inhibitor) and Curcumin, a novel approach that has not been previously explored in other types of cancer." (PMID 39211773, 2024). "The current standard first-line treatment for hormone receptor-positive/human epidermal growth factor receptor 2 negative (HR + /HER2 −) advanced breast cancer (ABC) is a combination of aromatase inhibitor (AI) plus CDK4/6 inhibitors (CDK4/6i)." (PMID 39152401, 2024). "Indeed, MPM_36 was the only pRb‐deficient palbociclib‐resistant cell line that presented a detectable phosphorylation of CDK4; reproducing the exceptional situation observed in DU4475 breast cancer cells." (PMID 36453028, 2024). "Although RET has been associated with ER+ breast cancer tumorigenesis and endocrine treatment response, the role of RET in resistance mechanisms to combined fulvestrant and CDK4/6i has not been evaluated." (PMID 39931212, 2024). "The present study aimed to evaluate the cost-effectiveness of CDK4/6 inhibitors in combination with letrozole as a first-line treatment for hormonal receptor-positive and HER-2-negative advanced breast cancer in addition to evaluating their cost-effectiveness versus one another." (PMID 39114308, 2024). "Hence, it is interest to document the molecular docking analysis of SR9009 (a pyrrolederivatives) with different breast cancer target protein targets such as HER2, Erα, PR, PI3K, AKT, Reverbα, BRMS1, Aromataseand mTOR, CDK4, CDK6, TK and Top II." (PMID 40230904, 2024). "Consequently, inhibiting CDK4/CDK6 can enhance the tumor-suppressive function of RB1, as demonstrated in breast cancer treatment." (PMID 39664374, 2024). "To evaluate the proportion of MPM patients that would be potentially responsive or intrinsically resistant to CDK4/6 inhibition, we determined the CDK4 modification profile from frozen MPM tumours and normal pleura samples as investigated previously in breast cancer." (PMID 36453028, 2024). "We systematically searched PubMed, Embase, and Cochrane Library for randomized controlled trials (RCTs) comparing the prevalence of QTc prolongation as an adverse event in HR+ breast cancer patients treated with CDK4/6i vs those without CDK4/6i." (PMID 39254653, 2024). "Unfortunately, NUP37 knockdown was not effective in MCF7 cells or another luminal breast cancer line (T47D), preventing further interpretations about CDK4." (PMID 39333715, 2024).
breast cancer (continued). "Cyclin-dependent kinase 4/6 inhibitors (CDK4/6i) combined with endocrine therapy have shown significant clinical benefits in terms of progression-free survival (PFS) and overall survival (OS) for hormone receptor (HR)-positive advanced breast cancer." (PMID 39133334, 2024). "Clinical studies have shown that adding CDK4/6i to endocrine therapy improved progression-free survival (PFS) and overall survival (OS) compared to endocrine therapy alone in patients with ER+ advanced breast cancer." (PMID 39931212, 2024). "All three CDK4/6 inhibitors (palbociclib, ribociclib, and abemaciclib) are currently approved by the United States Food and Drug Administration (FDA) for the treatment of breast cancer." (PMID 38605349, 2024). "The standard first-line treatment for patients with metastatic ER-positive, HER2-normal breast cancer (and no imminent organ failure) is combination therapy with CDK4/6 inhibitors and endocrine therapy." (PMID 38912829, 2024). "Since extended treatment with the HER2 inhibitors results in the suppression of HER2 expression, we questioned whether prolonged treatment with an HER2 inhibitor lapatinib sensitizes HER2+ breast cancer lines to combined TAM/Met and CDK4/6 inhibition." (PMID 38927958, 2024). "Furthermore, a recent investigation on breast cancer demonstrated that miR-34c targets CCND1, CDK4, and CDK6, pivotal cell cycle regulators that prompt arrest at the G2/M stage." (PMID 39097731, 2024). "Aberrant activation of the cyclin-dependent kinase 4 and 6 (CDK4/6) pathway, independent of mitogenic signaling, engenders uncontrolled breast cancer cell proliferation." (PMID 38409585, 2024). "Cyclin-dependent kinase 4 and 6 inhibitors (CDK4/6is) have revolutionized breast cancer therapy." (PMID 38443662, 2024). "Cyclin-dependent kinase 4/6 inhibitors restore the cell cycle by selectively inhibiting CDK 4 and 6 and blocking cell proliferation in a variety of tumor cells, including those of breast cancer." (PMID 39338149, 2024). "Hence, high levels of cyclin D1, CDK4, and CDK6 are often observed in most patients with breast cancer." (PMID 39328201, 2024). "mTOR inhibitor and CDK4/6 inhibitor-based regimens demonstrated superior clinical efficacy and comparable safety profiles as second-line treatment in patients with HR-positive, HER2-negative advanced breast cancer." (PMID 37644396, 2023). "To confirm the relationship between PARP1 and CDK4/6i resistance over a wider range, we obtained the IC50 for the CDK4/6i palbociclib in 30 breast cancer cell lines from the GDSC database and paired them with corresponding PARP1 mRNA level data gained from CCLE." (PMID 38037159, 2023). "CDK4/6 inhibitors (CDK4/6i), such as palbociclib, ribociclib, and abemaciclib, have been approved by the FDA and have emerged as promising treatments for patients with HR + /HER2- breast cancer." (PMID 38037159, 2023). "Finally, we identified several potential therapeutic drugs for breast cancer patients in high-ACI group through CMap, including Palbociclib targeting CDK4/6 and Lapatinib targeting EGFR." (PMID 37469408, 2023). "Thus, in clinical practice, inhibition of CDK4 and CDK6 has been an effective way of treating advanced HR+, HER2- breast cancer." (PMID 37296790, 2023). "Thus, CDK4/6 is an effective anticancer drug target, especially in hormone receptor-positive and human epidermal growth factor receptor 2-negative (HR+/HER2-) breast cancer." (PMID 37234717, 2023). "Our results support camizestrant's potential to be a superior backbone ET in naïve, early-stage disease, as well as in late-stage ER+/HER2− breast cancer tumors that have progressed on current ETs with/without CDK4/6i." (PMID 37725704, 2023). "Hence, with the rapid development of small-molecule drugs such as tyrosine kinase inhibitors (TKIs) and CDK4/6 inhibitors, additional chemo-free strategies are being developed for the treatment of HER2+/HR+ breast cancer." (PMID 36602226, 2023).
breast cancer (continued). "Especially in the treatment of patients with hormone receptor (HR)-positive and ERBB2 (formerly HER2)-negative advanced breast cancer, CDK4 and CDK6 inhibitors (abemaciclib, ribociclib, and palbociclib) have an important role." (PMID 36945921, 2023). "Disparities in survival and clinical outcomes between African American and White patients with breast cancer (BC) are well documented, but African American patients have not been well represented in randomized clinical trials of CDK4/6 inhibitors." (PMID 37487056, 2023). "That said, patients with PIK3CAmut HR+, HER2− advanced breast cancer have been shown to benefit from treatment with the p110α inhibitor alpelisib plus fulvestrant, regardless of prior treatment with a CDK4/6 inhibitor." (PMID 36892268, 2023). "The efficacy results of several trials have been uneven in the metastatic scenario, despite the FDA’s approval of the CDK4/6 inhibitors palbociclib, ribociclib, and abemaciclib for the treatment of patients with metastatic HR-positive/HER2-negative breast cancer." (PMID 37759823, 2023). "While the addition of CDK4/6i to endocrine therapy in the front-line setting has been a needed advancement for patients with advanced HR+ breast cancer, there is no standard of care for second-line therapy." (PMID 36980743, 2023). "Combining the selective AKT inhibitor, capivasertib, and SERD, fulvestrant improved PFS in a Phase III clinical trial (CAPItello-291), treating HR+ breast cancer patients following aromatase inhibitors, with or without CDK4/6 inhibitors." (PMID 37543694, 2023). "Several phase 3 trials have demonstrated the utility of combining a CDK4/6 inhibitor, including ribociclib, palbociclib, abemaciclib and dalpiciclib, with endocrine therapy as a second-line treatment for HR-positive, HER2-negative advanced breast cancer." (PMID 37644396, 2023). "Second, the lack of another control group of patients with breast cancer who were not taking CDK4/6i, is a limitation." (PMID 37046661, 2023). "Data suggest that cotargeting CDK4/6, PI3K/AKT/mTOR, and ERα could effectively control tumor growth in ER+ breast cancer xenografts and PDX models." (PMID 37725704, 2023). "However, the questions of whether endocrine therapy or CDK4/6 inhibitors are able to induce DNA damage, alter the chromatin landscape of DNA repair proteins and modify histones and importantly, how these might affect global transcription in ER+ breast cancer cells still remain." (PMID 37914699, 2023). "The addition of CDK4/6 inhibitors to ET is efficacious in suppressing cell proliferation, delaying cancer progression and improving survival, and represents the current standard of care first-line therapy for advanced ER+/HER2-breast cancer." (PMID 37035239, 2023). "After treatment with SKACP003, the CDK-4 and CDK-6 genes were significantly downregulated in the breast cancer cell lines compared to the control cell lines, indicating an anti-proliferative activity in all breast cancer cell lines tested." (PMID 36770598, 2023). "For example, about 20% of breast cancer patients receiving CDK4/6 inhibitor treatment have no response to treatment." (PMID 38138549, 2023). "Mice lacking CCND1 or CDK4 were resistant to mammary tumor development driven by the HER2 oncogene, suggesting CCND1 as potential therapeutic target for HER2+ BC as well." (PMID 37438342, 2023). "Results in early breast cancer are discordant, with sustained improvement in invasive disease-free survival demonstrated for abemaciclib but not other CDK4/6 inhibitors to date." (PMID 37369022, 2023). "Three CDK4/6 inhibitors (abemaciclib, palbociclib and ribociclib) have shown clinical benefit in patients with advanced hormone receptor (HR)-positive/HER2-negative breast cancer when given in combination with endocrine therapy." (PMID 37298520, 2023).